TCF7 (transcription factor 7)
Diseases named in the same sentence as TCF7 in open-access papers (continued):
Sharing a sentence is not in itself a finding about the gene and the disease.
tumor (173 papers, 2011 to 2026). "CAR-T treated with the demethylating agent decitabine have enhanced proliferation and anti-tumor function, which was associated with altered methylation at key loci, including TCF7, IL-7R, BCL6, and EOMES." (PMID 40307913, 2025). "Then, we investigated the single nucleotide variant (SNV) frequency of TCF4, TCF3, and TCF7 in each tumor based on TCGA data." (PMID 39205642, 2024). "In cancer patients, we found that TCF7, a signature gene for stem cell like exhausted T cells, was more highly expressed in PBMCs than in tumour cells, whereas Egr2 expression was specifically associated with the TME." (PMID 36342511, 2023). "Here we used Pdcd1 expression (which encodes for PD-1) as a surrogate marker of tumor specificity and observed that indeed, Pdcd1+ Havcr2– Slamf6+ cells were enriched in Tcf7+ cells compared to bulk Pdcd1+ or Pdcd1+ Havcr2– cells." (PMID 32174925, 2020). "• Two distinct states of CD8+ T cells were defined by clustering and associated with patient tumor regression or progression; • TCF7 was visualized within CD8+ T cells in fixed tumor samples and predicted positive clinical outcome." (PMID 32265933, 2020). "Next, we assessed expression of hallmark memory T cell stemness gene, transcription factor 7 (Tcf7), that has been associated with a superior ability of T cells to control tumor growth." (PMID 31779147, 2019). "Two GZMK+ clusters, GZMK+ early-activation CD8 T cells and GZMK+ late-activation CD8 T cells, are also clonal, tumor-associated, and exhibit signatures that resemble an intermediate stage between activation and exhaustion, reflected by their intermediate level of TCF7 and CD27 expression." (PMID 40610460, 2025). "T cell factor 1 (TCF1, encoded by the TCF7 gene) can be used as a critical determinant of successful anti-tumor immunotherapy and a prognostic indicator in some solid tumors; however, the effects of TCF1 in CLL remain unclear." (PMID 36211334, 2022). "The overexpression of TCF7 is also associated with tumor formation." (PMID 36457029, 2022). "The dual roles of TCF7 in tumorogenesis could be explained by the different functions of variant isoforms of TCF7 and the complexity of tumor variations with multiple signaling pathways in the process of tumor development." (PMID 26289446, 2015). "PLAC1 is associated with placental development, TCF7 is involved in T cell differentiation, and PLEKHA5 has been linked to the suppression of tumor metastasis." (PMID 40607388, 2025). "Subsequent RNA velocity analysis of the scRNA‐seq data indicated that TCF7+ Treg cells served as the starting point for the differentiation of various phenotypes of Treg cells in the tumor microenvironment." (PMID 39783838, 2025). "For example, effector-like TCRγδ+ cells in the colon demonstrated anti-tumor activity which was suppressed by Tcf7 expression." (PMID 40837586, 2025). "The results suggested that the Mg-Ca-nHAC composite scaffolds exerted anti-tumor effects by inhibiting Wnt/β-catenin/TCF7 signaling pathway." (PMID 41367628, 2025). "This study also shows that Mg alloy composite scaffolds’ degradation products target EMT through the Wnt/β-catenin/TCF7 signaling pathway, making it have potential anti-tumor properties." (PMID 41367628, 2025). "A separate study exploring single cell RNA sequencing of TILs in NSCLC tumors reported that a proportion of the tumor specific T cell clones can express TCF7." (PMID 40944710, 2025). "These cells express high levels of Tcf7 and β-catenin, undergo self-renewal, and differentiate into Th1-like effector progeny, processes that are essential for tumor eradication and autoimmune responses." (PMID 40634636, 2025). "Next, we examined TCF4 and TCF7 expressions in normal and tumor tissues across TCGA cancer types, respectively, using the RSEM expression value." (PMID 39205642, 2024).
tumor (continued). "In contrast, the central memory T cell (Tcm) cluster was represented by cells expressing TCF7, ANXA1, LEF1, and SELL genes and is commonly associated with central memory and tumor inhibition function." (PMID 37615858, 2024). "The lncRNA lncTCF7 has been shown to promote tumor progression by recruiting the SWI/SNF complex to the TCF7 promoter, activating its expression and the WNT signaling pathway." (PMID 39169000, 2024). "High expression of SLAMF6 is associated with increased expression of Teff-related genes and TCF7 which marks tumor-infiltrating T cells with stem cell-like properties." (PMID 38287061, 2024). "Although the fetal tumor cluster displayed some regulon activity for TCF7 and TCF7L2, this was notably less pronounced compared to the embryonal tumor cluster." (PMID 39567475, 2024). "The CD8_G state was characterised by TCF7 expression, and infiltration of TCF7+ CD8 T cells was associated with better tumour regression." (PMID 38241976, 2024). "These included a major Prf1highGzmhighPdcd1+Havcr2+ cluster resembling “exhausted” T (TEX) cells and a Pdcd1+Tcf7+Slamf6+ cluster resembling “stem-like” T cells, that were predominantly tumour-resident and expanded with anti-PD-L1." (PMID 38267413, 2024). "With a different exogenous WNT-responsive reporter approach on the same CRC cell lines, TCF7 was identified as a positive regulator of CRC while TCF7L2 was shown to have tumor suppressor properties in CRC17." (PMID 38472198, 2024). "The AR is a direct regulator of Tcf7, and its signalling induces the sex‐biased generation of the Tpex cell subset with impaired tumour control." (PMID 39169517, 2024). "The knockdown of Tcf7 not only weakened the anti-tumor potential of Pmel-CD38−/− T cells but also compromised their responsiveness to anti-PD1 therapy." (PMID 38451948, 2024). "LncTCF7 promotes the expression of a neighbouring gene, WNT signaling factor TCF7, and drives tumor growth and cancer progression in mouse models." (PMID 39169000, 2024). "PDCD1 and TCF7 were overrepresented in mTLSs as compared to eTLSs and nTLS areas in 3 independent tumor samples, with a similar but subsignificant trend for HAVRC2." (PMID 38514660, 2024). "In contrast, tumor-associated CD8+ T cells show substantially decreased expression of cytotoxic genes and higher expression of the exhaustion marker gene Tcf7, indicating a dysfunctional state." (PMID 37143122, 2023). "We then queried scRNA-seq datasets from healthy and PDA-bearing mice and similarly detected Tcf7 in T cells, with an increase in its expression in tumor samples." (PMID 36239683, 2023). "In the absence of migration from the tdLN there was equivalent control of B16 tumours over a period of 6 days and this required the presence of Tcf7+ TPEX within the TME." (PMID 37139854, 2023). "PD-1+ CD8+ T cells in tumor tissues are required for this T-cell immune status, and recently, transcription factor 7 (TCF7)-positive PD-1+ precursor-exhausted CD8+ T cells have been considered important for the therapeutic efficacy of PD-1 blockade." (PMID 37476074, 2023). "Tumor growth was similar in Cd4;Tcf7fl/fl mice treated with anti–PD-L1 antibody compared with Cd4;Tcf7+/+ mice on the same treatment, possibly indicating that other compensatory mechanisms limit antitumor responses in this model." (PMID 36239683, 2023). "It has been reported thatLEF1, TCF4, and TCF7 areinvolved in the maturation and malignant transformation of thymocytes, developmentof natural killer and T cells, and through Wnt pathway, tumor infiltration andimmune evasion." (PMID 38100720, 2023). "We found that when co-cultured with CD4+ T cells from tumors in Cd4;Tcf7+/+ mice, 7940b cells expressed more Cd274 compared with tumor cells cultured alone." (PMID 36239683, 2023). "A tumour-specific upregulation of Lef1 and Tcf7 genes was observed, as well as downregulation of Tcf7l1, while Tcf7l2 expression was unaltered." (PMID 37907668, 2023).
tumor (continued). "We then isolated CD4+ T cells from the spleen, lymph nodes, and blood of healthy mice and tumor-bearing mice and investigated the expression of Tcf7, Lef1, and Axin2." (PMID 36239683, 2023). "Studies have shown that androgens can promote the exhaustion of CD8+T cells by regulating the transcription factor Tcf7, thereby promoting tumor growth." (PMID 36992839, 2023). "They examined the expression levels of TCF7 in CD8+ T cells and found more tumor-infiltrating TCF7+ CD8+ T cells in ICB responders and more TCF7− CD8+ T cells in non-responders, demonstrating the predictive ability of TCF7 expression of CD8+ T cells." (PMID 38066642, 2023). "Using the Kaede mice to label intra-tumoural immune cells in a subcutaneous model of colon cancer, they showed that Tcf7+ TPEX can reverse migrate back to the tdLN potentially seeding the tdLN-derived tumour-specific memory cells (TSM) population there." (PMID 37139854, 2023). "Overall, T cells in the irradiated tumor had a more memory- or progenitor-like phenotype compared with the untreated tumor, with higher expression of genes encoding TCF-1 (TCF7), CD127 (IL7R), and L-selectin/CD62L (SELL)." (PMID 37209684, 2023). "Transcription factor 7 (TCF7), the T-cell–specific transcription factor required for T-cell development in animal models, suggests that it probably functions as a tumor suppressor." (PMID 36186463, 2022). "Several reports have shown both TCF7 and CTNNB1 is implicated in tumor formation and metastasis in several types of cancer." (PMID 36457029, 2022). "The specific mechanism by which TCF7+ T cells affect tumor prognosis is currently unclear, warranting further investigation in combination with single-cell sequencing and other technologies to explore the specific mechanism of TCF7." (PMID 35345446, 2022). "In human cancer liver stem cells, the lncTCF7 recruits the core subunits of the SWI/SNF complexes to the TCF7 promoter and promotes tumor progression." (PMID 33958593, 2021). "Surveys of TIL heterogeneity using single-cell RNA sequencing (scRNA-Seq) have indicated that activated, expanded, and exhausted CD8+ T cell subsets are variably present in different tumor samples and effectively cluster based on Tcf7 expression." (PMID 34354714, 2021). "TCF7 and CYLD (a tumor suppressor) were both strong predictors of risk of progression to cancer in this study." (PMID 36860910, 2021). "A Tcf7-diphtheria toxin receptor (DTR) system was creatively designed to deplete tumor-specific TCF1+CD8+ T cells." (PMID 34512656, 2021). "The exception to this rule is a strengthened correlation between AXIN2 and TCF7 expression in tumor tissue." (PMID 32403323, 2020). "In particular, GAD_CD14 derived gene signature indicates that the location of monocytic cells correlates with the distribution of TCF7 memory stem-like lymphocytes and tumor specific T cells." (PMID 33193316, 2020). "Our meta-analysis confirms that among the four human LEF/TCF genes, LEF1 and TCF7 are preferentially expressed in tumor biopsies, while TCF7L2 and TCF7L1 in normal control tissue." (PMID 32403323, 2020). "In HCC, lncTCF7 recruits the SWI/SNF chromatin remodeling complex to TCF7 promoter to regulate TCF7 transcription, activating the Wnt signaling cascade and thus priming liver CSCs self-renewal and tumor propagation." (PMID 32549757, 2020). "The analysis also reveals a likely feedback loop in tumor tissue from WNT/β-catenin/TCF7 signaling mediated transcriptional regulation in the nucleus to resulting changes in WNT receptor protein abundance at the membrane." (PMID 32403323, 2020). "A previous report already showed that tumor-specific (identified by tetramer staining) Tim3- Slamf6+ cells were enriched in Tcf7+ cells compared to Tim3+ Slamf6- counterparts." (PMID 32174925, 2020).
tumor (continued). "In particular, the age-related inhibition of TCF7 expression by methylation not only plays an important role in immune enhancement and tumor suppression, but also in balancing blood glucose levels and hematopoiesis." (PMID 33188156, 2020). "To investigate the effects of TCF7 expression on tumor growth and histology, we performed xenograft assays." (PMID 31519911, 2019). "Increased expression of Tcf7, and its co-operating transcription factor Lef1, were further confirmed by quantitative PCR analysis in different EμMyc/Casp2−/− tumor samples." (PMID 30670683, 2019). "Similar to shTP63, we tested mammary fat pad, intraductal, and subcutaneous injections to see how the microenvironment influences tumor growth and histology, and we induced TCF7 at day 1 or day 10 after injection." (PMID 31519911, 2019). "To assess if this tumor epithelial expression of TCF7 is maintained during invasive progression, we also analyzed invasive tumors of different subtypes." (PMID 31519911, 2019). "Depletion of TCF7 resulted in an increase in adenoma formation in the adult gut and markedly increased tumor incidence in multiple intestinal neoplasia (min) mice, which are heterozygous for a stop codon in the tumor suppressor gene APC (Apcmin)." (PMID 27527215, 2016). "Mice deficient in the TCF7 gene develop intestinal and mammary adenomas, suggesting a role for TCF7 as a tumor suppressor." (PMID 24883311, 2014). "While the Lef1 gene was moderately upregulated in transgenic and tumor cells, Tcf7 showed significant upregulation in tumor." (PMID 21464922, 2011). "Similarly, studies on hematologic malignancies have demonstrated that REGNASE-1 directly targets TCF7 mRNA, and its deficiency promotes TCF-1 expression, thereby enhancing the persistence of anti-tumor response of CAR-T cells." (PMID 41250215, 2025). "Aldometanib did not affect the numbers of stem-like CD8+ T cells (PD-1+CD44+Tim3−Tcf7+) or terminally exhausted CD8+ T cells (CD8+ Tex; PD-1+CD44+Tim3+Tcf7−), indicative of the presence of long-lasting anti-tumor immunity and an effective immune surveillance mechanism." (PMID 41286115, 2025). "In cancer immunology, TCF7+ CD8+ T cells are thought to play a key role in promoting effective antitumor immunity by preserving a reservoir of memory T cells capable of rapidly responding to tumor antigens." (PMID 39789615, 2025). "Furthermore, these defects enhanced tumor cell survival by the activation of Wnt and anti-apoptotic signaling pathways leading to the expression of TCF7 and BIRC5." (PMID 38577343, 2024). "Additionally, ATAC‐seq and gene array analyses have further uncovered that CLF amplifies the anti‐tumour capacity of tumour‐specific CD8+ T cells through the upregulation of E2F1‐induced Tcf7 promoter activation." (PMID 38965409, 2024). "PRDM1, also known as B lymphocyte-induced maturation protein 1 (BLIMP1), has been shown to impair the stemness and growth activity of CAR T cells, as indicated by TCF7, which is closely associated with the exhaustion phenotypes of CAR T cells in anti-tumor therapies." (PMID 39678513, 2024). "Elevated frequencies of TCF7+CD8+ T cells in fixed tumor specimens predict positive outcome." (PMID 37881432, 2023). "CD8+ TMs expressing CCL5 and GZMA, MAIT (mucosal‐associated invariant T) cells expressing TCF7 and PLAC8, and CD4+ TNs (Naïve T cells) expressing CCR7 appeared in paratumour tissues, while CD4+ISG+ T cells expressing ISG15/20 and CD8+ TNs expressing TCF7 only appeared in tumour tissues." (PMID 36855810, 2023). "By contrast, CD4+ Th cells from CAR T-vax-treated mice upregulated genes associated with Th1 function (Ifng, Cxcr3) and self-renewal (Slamf6, Tcf7), suggesting that the vaccine may also promote anti-tumor phenotypes among CD4+ TILs." (PMID 37413990, 2023). "In addition, it was found that Co-A15-Exo notably downregulated TCF7 protein expression in cells and significantly inhibited tumor cell growth and tumor angiogenesis." (PMID 38047286, 2023).
tumor (continued). "Interestingly, genes of Wnt signaling pathways including FZD7 and TCF7 are upregulated in tumor-adjacent stroma as compared to tumor epithelium." (PMID 36230846, 2022). "Lef1- and Cbx3-Lef1-deficient mice, in which Tcf7 is not deleted, fail to control tumor growth suggesting that Lef1 function is not redundant." (PMID 34721405, 2021). "However, differences in TCF7 isoform expression between normal and tumor tissue have been described, and our analysis is at least consistent with a different mix of TCF7 isoforms being expressed in normal and tumor tissue." (PMID 32403323, 2020). "Therefore, our findings suggest that the close proximity between monocytic myeloid and cytotoxic T cells reflects tumor stromal co-localization of CD11b+CD14+ myeloid cells with CD8+TCF7+ stroma-residual stem cell-like T cells." (PMID 33193316, 2020). "We ranked the TCF7 gene expression-correlated whole transcriptome expression (positively and negatively correlated) separately in normal tissue and in tumor tissue, and then also independently ranked and analyzed the greatest transcript correlation differences between tumor and normal tissue." (PMID 32403323, 2020). "Our meta-analysis of transcriptomics studies provides a clear picture of altered LEF/TCF gene expression, confirming TCF7L2 in normal and LEF1 expression in tumor tissue, but also higher than expected TCF7L1 in normal and relatively higher TCF7 expression in tumor tissue." (PMID 32403323, 2020). "The spatial analysis indicates that the location of monocytic cells correlates with the presence of TCF7 memory stem-like lymphocytes and tumor specific T cells, whereas spatial distribution of granulocytic cells associates with the activity of CD4+ lymphocytes." (PMID 33193316, 2020). "Thus, TCF7-positive T cells are tumor-specific CD8 cells that express PD-1 and other exhaustion-associated markers as a result of chronic activation but are able to functionally recover in response to PD-1 inhibition." (PMID 32089832, 2020). "Since TCF7 could suppress TCF7L2, it might be a promising anti-tumor strategy to introduce TCF7 to tumor cells as a treatment." (PMID 26289446, 2015). "In addition, androgens may also attenuate anti‐tumor immune responses through their effects on Tcf7/TCF1+ progenitor exhausted CD8+ T cells (Tpex)." (PMID 41580387, 2026). "Furthermore, multiple studies have reported that a self-renewal PD-1+ T cell population with stem cell properties that expresses TCF7 (coding for T cell factor 1) proliferates in the periphery and lymphoid organs and undergoes tumor antigen–driven expansion following anti–PD-1 therapy." (PMID 36647828, 2023). "Besides, RT had little effect on tumor-associated macrophages and CD8+ TCF7+ T cells." (PMID 35301438, 2022). "An interesting exception to this rule is the stronger association between TCF7 and AXIN2 expression in tumor tissue, which could suggest some specificity in TCF7-mediated WNT/β-catenin signaling in human tumor tissue, supporting earlier such suggestions in the mouse model." (PMID 32403323, 2020). "The AXIN2-correlated transcriptome in tumor tissue trumps however, in its association with transcripts indicating regulation of Wnt signaling, particularly Wnt receptor catabolic processes, and contrasting with all LEF/TCF-correlated transcriptomes, apart from, interestingly, that of TCF7." (PMID 32403323, 2020). "It was detected that the dominant TCF7 isoform had short-life and existed in both nucleus and plasma in normal cells such as proliferating intestinal epithelial cells and basal epithelial cells of mammary gland epithelium, while the full-length isoform in tumor cells and mainly appeared in plasma." (PMID 26289446, 2015). "Remarkably, TCF7, as well as other genes related to the activation and survival of CD8+ T cells, were enriched in tumor biopsies obtained from patients with metastatic melanoma responding to ICB treatment." (PMID 40299510, 2025).